CD274 (CD274 molecule)
Diseases named in the same sentence as CD274 in open-access papers (continued):
Sharing a sentence is not in itself a finding about the gene and the disease.
head and neck squamous cell carcinoma (489 papers, 2015 to 2026). A squamous cell carcinoma that arises from any of the following anatomic sites: lip and oral cavity, nasal cavity, paranasal sinuses, pharynx, larynx, and salivary glands. "Study reported that high-expressed CTLA4 and CD274 in head and neck squamous cell carcinoma (HNSCC) may cause immune dysfunction in the patients." (PMID 40173324, 2025). "CD274 was found to be strongly expressed in HNSC (head and neck squamous cell carcinoma), STAD (stomach adenocarcinoma), and ESCA (esophageal carcinoma)." (PMID 38166842, 2024). "Another homologous recombination gene, XRCC3, was identified to correlate with CTLA4 expression in all three cancer types but exceeded the cutoff for CD274 only in head and neck squamous cell carcinoma." (PMID 27683114, 2016). "Additionally, in silico analysis was performed based on the TCGA Head and Neck Squamous Cell Carcinoma (HNSCC) cohort in order to correlate patients’ survival with TIGIT and CD274 (encoding for PD-L1) gene expression levels." (PMID 36551992, 2022). "Compared with TIDE, MIS score, CD274, CD8, IFNG, and Merck18, DDX20 alone had a higher AUC (0.71) in head and neck squamous cell carcinoma (Uppaluri2020_PD1_HNSC_Pre)." (PMID 36246406, 2022). "In the analysis of immune checkpoint (IC) genes, PLAG1 exhibits a positive correlation with key IC genes such as HAVCR2 and CD274 in cancer types like LGG and PRAD, while showing a negative correlation in head and neck squamous cell carcinoma (HNSC) and STAD." (PMID 40276502, 2025).
prostate carcinoma (464 papers, 2012 to 2026). A carcinoma that arises from epithelial cells of the prostate gland. "pRB has been implicated in the control of PD-L1 via NF-kB in prostate cancer cells, whereby Ser249/Thr252-phosphorylated pRB binds and sequesters NF-kB (p65), preventing it from transcriptionally activating CD274." (PMID 37230983, 2023). "The expression dynamics of PD-L1 (CD274) in prostate cancer are complex and can vary depending on tumor stage, tumor microenvironment, and specific cellular contexts." (PMID 40034825, 2025). "Researchers compared the effects of exosomes extracted from wild-type and Cd274 (PD-L1) knockdown (kd) cell lines of TRAMP-C2 prostate cancer on mouse models." (PMID 38473281, 2024). "Other examples include the study of sera from prostate cancer patients where differentially expressed end points (e.g., programmed death-ligand 1 (PD-L1), CD274), survivin, and transforming growth factor beta were identified as deriving from T-EVs." (PMID 39147028, 2024). "These pathways were confirmed using prostate cancer and other cells expressing individual isoforms in which several immune signalling genes including CD274/PD-L1, and angiogenesis genes, were upregulated." (PMID 31431617, 2019). "Poly I:C, a synthetic double-stranded RNA analog, activates Toll-like receptor 3 (TLR3) signaling and enhances interferon responses; however, its impact on CD274 expression in prostate cancer remains unclear." (PMID 41409271, 2025).
lymphoma (458 papers, 2011 to 2026). A malignant (clonal) proliferation of B- lymphocytes or T- lymphocytes which involves the lymph nodes, bone marrow and/or extranodal sites. "In the case with composite EMZL and EBV‐positive DLBCL (case 6), both lymphomas harboured 23 common variants, including mutations in CD274, TET2, and TNFRSF14, and the EBV‐positive DLBCL showed an additional MYC translocation and a further 20 variants over the EMZL component." (PMID 39722652, 2025). "Similar with solid cancer, the responsiveness to anti-PD-1 therapies in lymphoma is also mainly determined by underlying biologic features of the lymphoma cell itself, such as overexpression of PD-1 ligands (i.e., PD-L1 encoded by CD274), as well as the composition of the TME." (PMID 36959853, 2023). "Most EBV‐driven lymphomas have high levels of programmed cell death protein 1 (PD‐1)/programmed death‐ligand 1 (PD‐L1) expression, typically due to latent membrane protein‐1‐mediated activation of the CD274 JAK/STAT‐dependent promoter or AP‐1‐associated enhancer activity." (PMID 38613207, 2024). "JQ1 decreased PD-L1 expression through BRD4-dependent occupancy of the CD274 promoter, thereby increasing tumor-associated CD8+ T cells producing IFN-γ and granzyme B in lymphoma, prostate, and oral squamous cell carcinoma models." (PMID 41583469, 2025). "Similar features were found in our study, showing that the coding gene CD274 of PD-L1 was rearranged in 23.81% (5/21) RR ENKTL.CD274 rearrangement has also been reported in adult T-cell leukemia/lymphoma and primary mediastinal large B-cell lymphoma." (PMID 35619907, 2022). "We examined the 19 cases with associated SVs for fusions involving either CD274 or PDCD1LG2, and we identified a putative fusion transcript for RNF38->PDCD1LG2 involving three cases, all of which were lymphoma." (PMID 32024823, 2020). "Chromosome 9p24.1 includes the loci of CD274 (encoding the PD-L1 checkpoint) and PDCD1LG2 (encoding PD-L2), and structural variants (SVs) affecting this region have proven amongst the most reproducible indicators of ICI response in lymphoma." (PMID 41295262, 2025). "However, overexpression of PD-L1 in lymphoma is commonly attributed to copy number gain of 9p24.1 (contained CD274), which is rarely seen in solid cancer." (PMID 36959853, 2023). "Moreover, the blockers of CD274 (PD-L1) have been widely tested in patients with a variety of lymphomas, and the blockers of PD-L1, nivolumab, and pembrolizumab have been proven effective for the treatment of recurrent or refractory lymphomas." (PMID 35069971, 2022). "Furthermore, NPM-ALK(+) lymphoma cells highly express the immunosuppressive cell-surface receptor PD-L1 also called CD274/B7-H1 which is physiologically expressed by immune cells and binds PD1, present on the surface of CD4+ and CD8+ lymphocytes." (PMID 33466277, 2021). "Genomic alterations involving the PD-L1 (B7-H1, CD274) locus, particularly gene amplification, lead to significant PD-L1 expression in subsets of aggressive B-cell NHL, while lymphoma-associated macrophages within the tumor microenvironment are an abundant source of PD-L1 in others." (PMID 28031823, 2016). "Downregulated genes in the absence of EBV in children included genes associated with key immune regulators (IL-10) and immune checkpoint genes (LAG3 and CD274), suggesting the impact of EBV infection in the modulation of immune response in pediatric lymphomas." (PMID 40461625, 2025). "To batch-normalize the three lymphoma patient samples, the mean expression of the three most stable channels—CD127, CD274, and CD137—were aggregated to define the universal reference and subsequently normalized using the MSFTB normalization function." (PMID 35177627, 2022). "miR-34a also binds to 3' UTR of CD274 and lowers PD-L1 expression in acute myeloid leukemia (AML) and lymphoma." (PMID 34088360, 2021).
lymphoma (continued). "PD-L1 (CD274) and PD-L2 (PDCD1LG2 or CD273) are variably expressed by malignant lymphoma cells and are the cognate ligands for PD-1 expressed on CTLs." (PMID 33804869, 2021). "BET inhibitor (BETi), JQ1, also limited PD-L1 transcription by decreasing BRD4 occupancy at CD274 promoter without changes in MYC occupancy in lymphoma." (PMID 34088360, 2021). "The roles of B7-H1 (CD274, PD-L1) and B7-DC (CD273, PD-L2) in lymphoma are far less ambiguous." (PMID 25941795, 2015).
cervical carcinoma (444 papers, 2011 to 2026). A carcinoma arising from either the exocervical squamous epithelium or the endocervical glandular epithelium. "Elevated CD274 expression and impaired T-cell function have also been reported in HPV-associated head and neck squamous cell carcinomas (HNSCCs) and cervical cancer." (PMID 39911394, 2025). "DNA status analysis by FISH showed that most of the evaluable cervical cancer cases had disomy of chromosome 9 with two signals for both the CD274 (PD-L1) and PDCD1LG2 (PD-L2) locus (n = 43, 81%)." (PMID 33424844, 2020). "The ENO1 regulator gene, which we found to be overexpressed in cervical cancer, positively correlated with PD-L1 (CD274) and TGFB1 in both data sets, providing further indication for immunotherapy targeting in this malignancy." (PMID 28670312, 2017). "Previous research has reported high expression of CD274 in tumor tissues of HPV-related cervical cancer patients, and the HPV proteins may be involved in CD274 regulation." (PMID 39911394, 2025). "Moreover, H3K4me2 levels in the CD47/CD274 promoters of SiHa and C33A cells further increased after LSD1 knockdown, suggesting a direct regulatory effect of LSD1-mediated H3K4 demethylation on CD47 and PD-L1 expression in cervical cancer." (PMID 33731702, 2021). "Additionally, we found that PD-L1 (also referred to as CD274) might mediate the cancer-promoting effect of EphA2-CXCL11 in cervical cancer." (PMID 36478746, 2022). "In cervical cancer patients, we found CSCC cohorts obtained higher TMB score, MSI score and common inhibitory checkpoints expression (e.g., PDCD1, CD274, BTLA, CTLA4, TIGIT, etc.), accompanied by more abundant immunocytes infiltration." (PMID 38206304, 2024). "In cervical cancer, TGCA amplifications in CD274 (PD-L1) and PDCD1LG2 (PD-L2) immune targets were found to be associated with this type of cancer, and PD-L1 amplification and polysomy have been shown to represent valid prognostic biomarkers in the treatment with anti-PD-L1s." (PMID 37341812, 2024). "We observed that CD274, CEACAM1, LGALS9, PVR and TNFRSF14 were significantly different (P < 0.05) between two groups, providing a novel insight into immunotherapy for cervical carcinoma patients." (PMID 34789197, 2021). "Among those, ERBB2, CD274 (PD-L1), and PDCD1LG2 (PD-L2) had amplifications that highlight the potential for clinical trials of ERBB2 inhibitors and immunotherapeutic strategies for a subset of cervical cancers." (PMID 34680987, 2021). "Similarly, monocytes in healthy controls express only a small amount of PD-L1/CD274, whereas monocytes in cervical cancer patients show an increased expression." (PMID 33066260, 2020). "CD274 and PDCD1LG2 are immunotherapy targets with amplifications reported in cervical cancer." (PMID 28771191, 2017). "In cervical cancer, 7 genes were identified for CTLA4, 3 genes for CD274." (PMID 27683114, 2016).
metastatic disease (410 papers, 2015 to 2026). "Antibody‐based treatments in HNSCC, such as cetuximab (epidermal growth factor receptor; EGFR monoclonal antibody) or pembrolizumab (CD274; also known as PD‐L1 monoclonal antibody) are approved, but mostly in the recurrent/metastatic disease." (PMID 40437743, 2025). "Furthermore, CD274 simultaneously blocks Th1 and promotes Th2 infiltration in both, primary and metastatic tumors." (PMID 39544930, 2024).
squamous cell carcinoma (367 papers, 2014 to 2026). A carcinoma arising from squamous epithelial cells. "The established candidate gene lists were cross-validated in the respective other squamous cell carcinoma subtypes for the expression of CD274 and CTLA4." (PMID 27683114, 2016). "We observed higher expression of immune checkpoint ligands (PVR, NECTIN2, CD274, CD80, and CD86) in the tumor cells at the invasive front of the squamous cell carcinomas." (PMID 41309580, 2025). "Two homologous recombination genes, X-Ray Repair Complementing Defective Repair in Chinese Hamster Cells 3 (XRCC3) and RAD51 Paralog B (RAD51B) exhibited the highest correlation with CD274 and CTLA4 across all three squamous cell cancer types." (PMID 27683114, 2016). "Further investigations into the connection between methylation of DNA repair genes and CD274 and immunoregulatory gene expression are lacking to date in squamous cell carcinomas." (PMID 27683114, 2016). "Interestingly, in adenocarcinomas, but not in squamous cell carcinomas, RAS and MEK activation scores correlated with CD274 gene expression." (PMID 30972766, 2019).
metastatic melanoma (353 papers, 2013 to 2026). A melanoma that has spread from its primary site to another anatomic site. "It was found that IFN-γ-mediated CD274 upregulation and increased OS in metastatic melanoma were both significantly associated with CD8+ T cells." (PMID 36704353, 2022). "Metastatic melanoma secretes CD274-loaded extracellular vesicles to inhibit the function of CD8+ T cells and promote tumor growth." (PMID 39052013, 2024). "In summary, this study reports the promising association of individual immunotherapy panel markers CD274, PDCD1LG2, CD8A, IRF1 and a combined L1/L2 score (CD274 & PDCD1LG2) with improved immunotherapy outcome in metastatic melanoma." (PMID 31533832, 2019). "Furthermore, CD8+ T cells have been correlated both with increased overall survival (OS) in metastatic melanoma and an IFN‐γ‐mediated CD274 upregulation, suggesting them as promising candidates for the final model." (PMID 35802807, 2022).
urothelial carcinoma (327 papers, 2015 to 2026). A malignant neoplasm derived from the transitional epithelium of the urinary tract (urinary bladder, ureter, urethra, or renal pelvis). "The blockade of the immune checkpoint pathway involving the programmed death 1 (PD-1) receptor and its ligands, CD274 (PD-L1) and CD273 (PD-L2), has recently been shown to be effective in the treatment of various cancers, including urothelial carcinoma (UC)." (PMID 38067231, 2023).
lymph node metastasis (293 papers, 2015 to 2026). "CD274 and PDCD1LG2 not only impacted the prognosis of patients with cancer but were associated with clinical characteristics (lymph node metastasis, tumor stage, and sex) in kidney renal papillary cell carcinoma, thyroid carcinoma, and some other cancer types." (PMID 36276934, 2022). "Furthermore, high expression levels of CD274 and PDCD1LG2 were restrictively associated with lymph node metastasis in THCA and found to be associated with tumor stage in BLCA." (PMID 36276934, 2022). "In addition, a previous study demonstrated a similar association of CD274 and CD3G considering lymph node metastases and hypermutation, respectively." (PMID 35204406, 2022). "In contrast, PD-1 expression, CD274/PD-L1 copy number, pT category, presence of lymph node metastases or tumor grading were not relevantly associated with these risks (data not shown)." (PMID 26918453, 2016).
head and neck cancer (292 papers, 2012 to 2026). A primary or metastatic malignant neoplasm affecting the head and neck. "As shown, NNMT, FLI1, SLPI, LAMP3, SERPINA1, GAS6, and CD274 have been often used as biomarkers for OSCC or head and neck cancer, while other genes listed have seldom been investigated in oral cancer and may be considered as novel biomarkers for OSCC prevalence and treatment." (PMID 28286742, 2017). "Programmed death-ligand 1 (PD-L1; also called CD274 and B7-H1) is an immune checkpoint molecule, and it is highly expressed in head and neck cancer." (PMID 39329063, 2024). "Among genes potentially responsible for OSCC-GB progression, upregulation of immune checkpoint genes—CD274, CD80, and IDO1—was also observed in head and neck cancer patients." (PMID 33980865, 2021).
liver cancer (275 papers, 2008 to 2026). An epithelial or non-epithelial malignant neoplasm that arises from the liver. "Focusing on the transcriptional regulation of ISGs, recent findings in liver cancer indicate that the epigenetic modifier EZH2 can suppress PD-L1 expression by upregulating the level of H3K27me3 at the promoters of both the CD274 gene (which encodes PD-L1) and the IRF-1 gene." (PMID 40909948, 2025). "Analysis of 21 trogocytosis‐related proteins identified three with causal associations to liver cancer: HAVCR2, CD274, and C3." (PMID 40895144, 2025). "Further tumor microenvironment investigations based on a subcutaneous liver cancer mouse model identified that 125I therapy recruited Cd274/Pd‐l1+ neutrophils and induced T‐cell exhaustion, leading to immune evasion and brachytherapy resistance." (PMID 40878691, 2025). "HILPDA expression was positively correlated with TGFB1 and CD274 expression in liver cancer tissues." (PMID 33816230, 2021). "Moreover, the expression of SLC10A3 protein is correlated with stromal CD4 T cells, CD20 B cells, macrophages, PDCD1 (PD-1) and CD274 (PD-L1) expression, indicating a potential regulatory role in liver cancer immunotherapy." (PMID 38178258, 2024). "Moreover, we validated the expression of HILPDA and the correlation between the expression of HILPDA and TGFB1/CD274 using 13 paired samples from liver cancer patients." (PMID 33816230, 2021). "Not only that, studies have shown that EZH2 can also inhibit the expression of the immune checkpoint inhibitor PD-L1 by directly upregulating the levels of CD274 and IFN regulatory factor 1 (IRF1) promoter H3K27me3 in liver cancer cells." (PMID 37626362, 2023).